PBX1 (PBX homeobox 1)
Diseases named in the same sentence as PBX1 in open-access papers (continued):
Sharing a sentence is not in itself a finding about the gene and the disease.
adenocarcinoma (5 papers, 2011 to 2024). A common cancer characterized by the presence of malignant glandular cells. "Increased PBX1 expression has been observed in adenocarcinomas associated with poorly differentiated tumors or lymph node metastasis, suggesting that increased PBX1 expression correlates with malignant GC pathologies." (PMID 28514754, 2017). "Although Pbx1 expression is observed in adenocarcinoma, whether isoform specific expression of Pbx1 has any role in t-NEPC needs further investigation." (PMID 39183332, 2024). "Although PBX1 expression increases significantly from adenocarcinoma towards t-NEPC transformation, we questioned to understand what favors differential recruitment of PBX1 in Pax5 promoter in NE-like cells but not in adenocarcinoma." (PMID 38168280, 2023).
infection (5 papers, 2015 to 2023). The state of being infected such as from the introduction of a foreign agent such as serum, vaccine, antigenic substance or organism. "We also examined the Tr1 cell–associated transcription factor PBX1 and found that it suppressed proinflammatory cytokine production by activated CD4+ T cells at sites of infection and inflammation." (PMID 37917177, 2023). "Pbx1 restricts proinflammatory cytokine production by T cells during infection." (PMID 37917177, 2023).
hematologic malignancies (4 papers, 2019 to 2025). "This review summarizes the impact of PBX1 on the development of hematologic malignancies, its influence on prognosis, and its potential use as a therapeutic target." (PMID 41226583, 2025). "The mechanisms and interactions of PBX1 in both solid and hematologic malignancies remain significant areas of study." (PMID 41226583, 2025). "In the context of hematological malignancies, researchers have investigated its functional importance by employing mouse models that either lack PBX1 or have an excess of it." (PMID 41226583, 2025).
blood tumors (2 papers, 2024 to 2025). "This review summarizes current knowledge on PBX1’s role in the growth of both mature and immature hematologic neoplasms." (PMID 41226583, 2025). "We show that PBX1 and E2A-PBX1 induce the development of highly malignant and difficult-to-treat solid and blood tumors." (PMID 39129784, 2024). "The complexity of PBX1 makes it a compelling subject for further research to thoroughly elucidate the specific mechanisms by which this molecule governs cellular processes, its influence on the development of both mature and immature hematologic neoplasms, and its viability as a biomarker." (PMID 41226583, 2025).
kidney disease (1 paper, 2023). "Therefore, further research should help us understand the specific involvement of PBX1 in each type of kidney disease and to consider the renal pathophysiological changes caused by an altered PBX1 expression or pathogenic mutations." (PMID 37006624, 2023).
Respiratory diseases (1 paper, 2015). "Another example, topological module 11, with 4 genes, contains MEIS1, MEIS2 and PBX1, which are disease genes associated with Cardiovascular, Neurological, Psychiatric, Endocrine and Respiratory diseases, and these were also defined as a disease module." (PMID 26399914, 2015).
PBX1 also shares sentences with these, for which no sentence is quoted: adenocarcinoma in situ (2 papers); COVID-19 (2); deafness (2); Down syndrome (2); esophageal squamous cell carcinoma (2); genetic diseases (2); glioblastoma (2); lymphoid leukemia (2); atherosclerosis (1); basal cell carcinoma (1); Brachycephaly (1); Breast Invasive Carcinoma (1); Burkitt lymphoma (1); carcinoids (1); childhood leukemia (1); Chondroid syringomas (1); chronic hepatitis B (1); Cushing syndrome (1); demyelination (1); dental disorder (1); depression (1); Duane-radial ray syndrome (1); Ewing sarcoma (1); follicular lymphoma (1); graft versus host disease (1); gynecologic cancers (1); head and neck squamous cell carcinoma (1); hearing loss (1); heart disease (1); heart failure (1).
A further 39 diseases each share a sentence with PBX1 in 1 paper.